CD4 (CD4 molecule)
Diseases named in the same sentence as CD4 in open-access papers (continued):
Sharing a sentence is not in itself a finding about the gene and the disease.
cancer (continued). "A pan-cancer analysis of stromal heterogeneity was also able to predict the naïve CD4+ T-lymphocyte response to immunotherapeutic treatment." (PMID 39348343, 2024). "Tumor-associated typical DCs (cDCs) phagocytose apoptotic cancer cell debris and transport cancer-related antigens to the draining lymph node, exposing them to naive CD4+ or CD8+ T cells, priming and activating T cells." (PMID 39257589, 2024). "The increase in seric CD8+ T-cells compared to CD4+ T-cells translates into a greater presence of T-cells with cytotoxic capacity, essential for the immune response against cancer." (PMID 37171559, 2024). "Our study exhibited that DLAT expression was associated with CD4+ T cells, CD8+ T cells, Tregs, and cancer-associated fibroblasts in many cancers." (PMID 39574473, 2024). "The ability of CD4+ Tr1 cells to maintain tolerance has been well established in autoimmunity and chronic infections and has been suggested to contribute to cancer immunosuppression." (PMID 39048822, 2024). "The hypoxia score is progressively increased with the trajectory of CD4+ T cell differentiation in cancer patients." (PMID 38956900, 2024). "Like TNBC, MIF signaling between cancer luminal A cells and CD4+ or CD8+ T cells via CD74 complexes was elevated in the older cohort." (PMID 39483921, 2024). "The result indicates that high expression of SPOP profiles with higher CD4/8+ T infiltrating cells were correlated with a better survival in cancer patients." (PMID 39074086, 2024). "Myeloid-derived suppressor cells (MDSC) are detected in many cancer patients as well as in vivo cancer models and they serve to suppress the immune system by preventing CD4 and CD8 T cell activation." (PMID 38935134, 2024). "While qPB-engineered CAR-T cells derived from healthy donors generally exhibited CD8 enrichment, cancer patient-derived CAR-T cells had a balanced CD8/CD4 CAR-T ratio." (PMID 39190688, 2024). "The expression of the GARP gene in tumors enhances the activity of TGF-β and induces the differentiation of CD4+ T cells into Tregs in the cancer microenvironment, hindering the immune response." (PMID 39534095, 2024). "Tregs, another subgroup of CD4+T cells, are widely studied as immunosuppressive cells in cancer immunology." (PMID 39000005, 2024). "The main risk factors identified for any cancer, NADCs, and related mortality were advancing age, and longer duration of HIV infection, while lower CD4 cell counts (<200 cells/μl), was associated with both ADC and NADC occurrences." (PMID 38549952, 2024). "Increasing evidence suggests that immune cell infiltration, such as CD4+ T cells and B lymphocytes, plays a key role in various cancers, including GC." (PMID 38499384, 2024). "One of the most important components of anti-cancer immune responses, CD4+ memory T cells are required for successful cancer elimination." (PMID 39068453, 2024). "This study also emphasized the role of BMX in the infiltration of immune cells, such as B cells, CD8+ T cells, CD4+ T cells, macrophages, neutrophils, and dendritic cells, in certain cancers." (PMID 39347140, 2024). "CD4+ T cells exhibit multifaceted functions in anti-cancer immunity, contingent upon the functional specialization of different subtypes of CD4+ T cells." (PMID 38322265, 2024). "RAB42 overexpression is significantly correlated with weakly infiltrated macrophages, CD8+ and CD4+ T cells, neutrophils, Tregs and dendritic cells across various cancer types." (PMID 39101146, 2024). "Qu Y24 analyzed the TIME of ADC and SQCC with gene expression data from The Cancer Genome Atlas and found that the numbers of Tregs and M2 macrophages were higher in ADCs, whereas those of activated CD4 + T cells and M1 macrophages were higher in SQCC." (PMID 38424363, 2024). "GzmB+CD4+ T cells have recently been shown to play a role in immune-mediated killing and therapy response in cancer." (PMID 38968186, 2024).
cancer (continued). "The immune microenvironment landscape was found to be poor for both GEP NET G3 and GEP NECs, with a slight enrichment of CD4 and CD8 T cells in GEP-NECs and of cancer-associated fibroblasts and macrophages (M2-like) in GEP-NET G3." (PMID 38729995, 2024). "CD4+ T helper antigens are essential components of cancer vaccines, but the relevance of the source of these MHC class II-restricted antigens remains underexplored." (PMID 39040850, 2024). "We observed that CCNB1 expression significantly correlates with the infiltration levels of CD8+ T-cells, CD4+ T-cells, macrophages, neutrophils, myeloid dendritic cells, and B cells in many cancer types." (PMID 38581717, 2024). "Leveraging the regulatory and adaptive capabilities of CD4 + T cells forms the basis of various immunotherapeutic approaches, including vaccines and treatments for cancer and autoimmune conditions." (PMID 39155358, 2024). "While the decrease in cancer contributions can be reasonably expected (healthy controls), the drop in CD4/8+ T cell estimates can more likely be attributed to overfitting." (PMID 39177091, 2024). "CD4+ T cells are likely to be the driving force of the cancer immunity cycle, allowing for a continuous supply of cytotoxic lymphocytes(CTLs) to the TME." (PMID 39588306, 2024). "Anti-cancer benefits of CD4 + T-cell activation during immune surveillance have been discussed elsewhere." (PMID 39068453, 2024). "PTCL with a pronounced Tfh CD4 + component are cancers that are mostly detected only at late stage of disease." (PMID 39272178, 2024). "In 33 cancer types, mast cells, CD4+Th2 T cells, Tregs, and common lymphoid progenitors were positively correlated with CDK12 expression." (PMID 38503865, 2024). "In patients with metastatic breast cancer, Treg depletion followed by cancer antigen inoculation produces effective antitumor CD4+ T and CD8+ T cells." (PMID 39534095, 2024). "The selection criteria yielded 7 cell types for TNBC: iCAF, myCAF, basal cancer cells, macrophages, monocytes, CD4+, and CD8+ T cells (7×7=49 possible source/target cell combinations)." (PMID 39483921, 2024). "From a non-cancer immunological perspective, CD4+ T cells are instrumental in improving CD8+ T cell functionality and recruitment in multiple ways, including increasing antigen-presentation on dendritic cells." (PMID 38572312, 2024). "Our findings revealed that EphB4 knockdown in cancer cells polarizes CD4+ T cells towards the Treg phenotype and enhances Treg immunosuppression." (PMID 39091728, 2024). "Given the variance observed in Evar all between circulating and tissue-derived datasets, we sought to explain this by comparing the ab initio NMF in a pan-cancer dataset with the NMF defined in circulating CD4+ T cells." (PMID 38359792, 2024). "We validated the DNAJB1-PRKACA fusion protein as a source of HLA class I and HLA class II-presented antigens inducing both CD8+ and CD4+ T-cell responses, required for effective anti-cancer immunity." (PMID 38606105, 2024). "The basophils in TDLNs were observed, and the role of cancer-associated fibroblasts in releasing TSLP was noted, which in turn activated dendritic cells (DCs) to generate IL-3 from CD4* T cells." (PMID 39816393, 2024). "In agreement with this scenario, the presence of IFN-I-producing CD4+ T cells in the TME is associated with overall survival and the response to PD-1 checkpoint blockade in cancer patients." (PMID 38383773, 2024). "This can be achieved without triggering autoimmunity, through the integration of self-antigen-independent CD4+ T cell epitopes into cancer vaccines." (PMID 38473878, 2024). "The development of lymphocytes and the role of CD4+ T cell-derived EVs are pivotal in cancer dynamics." (PMID 39062046, 2024). "For example, the hypoxia score is negatively correlated with the abundance of CD4 T cells in 27 cancer types and with central memory T cells (Tcm) in 20 cancer types." (PMID 38956900, 2024).
cancer (continued). "Comparing cancer CM-treated NHDFs to untreated NHDFs showed a further increase in CD4 T cell proliferation with CM derived from VM15 and an increase-trend with CM derived from VM26 (not statistically significant)." (PMID 39516494, 2024). "For example, NMF7 (IFN-F) in circulating CD4+ T corresponded to NMF15 in ab initio NMF defined by the pan-cancer dataset." (PMID 38359792, 2024). "Dendritic cells stimulate an anti-cancer immune response by presenting antigens to T cells, activating both CD4+ helper and CD8+ cytotoxic T lymphocytes." (PMID 38254898, 2024). "Similar to PD-1, constitutive LAG3 expression is associated with exhausted T cells (CD4 and CD8 T cells) in cancer and chronic viral invasions." (PMID 39211038, 2024). "CD4 + T cells are believed to be the primary catalyst in the cancer immunity cycle, facilitating a continuous provision of CTLs to the TME." (PMID 39026211, 2024). "As an essential component of the pulmonary microenvironment and, due to their plasticity and intrinsic characteristics of coordinating the immune response, CD4+ T lymphocytes are responsive to changes in this site, which are important during cancer." (PMID 38690280, 2024). "While Treg cells account for just 2–5% of total CD4+ T cells in the peripheral blood of healthy individuals, they constitute 10–50% of CD4+ T cells in malignancies, with most of them being eTreg cells, as already mentioned." (PMID 39273452, 2024). "Although TH1 CD4+ TIL is thought to boost cancer immunity, the functions of TH17 and TH2 are extensively complex." (PMID 39712007, 2024). "The activation of CD4+ T cells for cancer immunoprevention and therapy offers several distinct advantages over conventional immunotherapies that target CD8+ T cells." (PMID 39507526, 2024). "This also holds for the role of TAM in the processing and presentation of cancer antigens to CD4+ T cells and the engagement of adaptive anticancer immunity." (PMID 38287290, 2024). "It has been reported that high infiltration of M0 macrophages, naïve CD4 T cells, gamma delta T cells and regulatory T cells (Tregs) is correlated with poor prognosis in cancer patients." (PMID 37612583, 2024). "A multicentre study that assessed cancer incidence after cART initiation in 11,485 patients reported a median CD4 count of 202 cells/mm3 (range 61–338 cells/mm3) at the moment of cancer diagnosis." (PMID 38406522, 2024). "This vaccine demonstrated effectiveness in mice and was capable of eliciting NY‐ESO‐1‐specific CD8+ and CD4+ T‐cell responses in cancer patients with pre‐existing NY‐ESO‐1 immunity." (PMID 39275923, 2024). "In pan-cancer analysis using the TIME and EPIC algorithms, UBR1 was found to be associated with various immune cells, particularly CD4+ T cells." (PMID 39181686, 2024). "Next, we compiled a cohort of ten scRNAseq datasets across six types of human cancer to confirm the presence of IFN-I-producing CD4+ T cells in the TME." (PMID 38383773, 2024). "The researchers found that this anti-cancer effect was due to an increase in CD4+ T cell, CD8+ T cell, and DC cell infiltration into tumors." (PMID 38552222, 2024). "The co-expression assay between immunocytes and clinical prognosis revealed that the fractions of M1 macrophages, resting dendritic cells, regulatory T cells (Tregs), and memory CD4+ T cells significantly differed among different cancer grades." (PMID 38495486, 2024). "As shown in these results, positive associations were observed between GLP-1 signaling scores and many T cells, such as CD4+ T cells, central memory T cells (Tcm), natural killer (NK) cells, Follicular helper T cells (Tfh), in most cancer types." (PMID 39104385, 2024).
cancer (continued). "Past reports on severe COVID‐19 also detected AIM + CD4 Treg and Th17 subsets, including one study on B‐mAB post‐therapy T‐cell immunity in 46 subjects (unspecified for malignancies)." (PMID 39659018, 2024). "The results showed that the expression level of LRP6 correlated with the infiltration level of immune cells such as T cells CD8+, T cells CD4+, neutrophils, macrophages, dendritic cells, etc., in 33 cancer types." (PMID 38226972, 2024). "Correlations were observed with CD4+ T cells in 25 different types of cancer, with CD8+ T cells in 25 types, macrophages in 26 types, neutrophils in 19 types and dendritic cells in 22 types." (PMID 39086142, 2024). "Our research expanded the mechanism of BCL6 in cancer progression, and highlighted the role of CD4+T cells in HCC immune surveillance." (PMID 38956432, 2024). "It plays a crucial role in stimulating the immune system’s anti-cancer defenses by boosting the activity of specific immune cells, including CD4+ T helper cells, CD8+ cytotoxic T cells, natural killer cells, dendritic cells, and macrophages." (PMID 38923980, 2024). "Cancer vaccines stimulate CD4+ T helper cells and CD8+ cytotoxic T lymphocytes to engage with TAAs to induce a specific adaptive immunologic response and to initiate immunologic memory to protect against further exposure to the antigens." (PMID 39722028, 2024). "Macrophages exhibited the most significant age-related interaction changes, marked by homotypic interactions and increased communication with cancer basal cells, monocytes, CD4+ T cells, and CD8+ T cells, despite their lack of ARPs." (PMID 39483921, 2024). "In cancer, a small population of CD4+CD25hiFOXP3+ Tregs expressing LAG-3 is preferentially expanded in the PBMCs of cancer patients compared to healthy controls as well as within the tumor bulk itself." (PMID 39346924, 2024). "CD4+ T cells further enable the hyperactivation of macrophages, promoting their ability to engulf dead cells and live cancer cells." (PMID 39627216, 2024). "The findings of this study indicate a positive correlation between the expression of AURKB and the level of CD4+ Th2 cells in various types of cancers, with the exception of TGCT." (PMID 38898693, 2024). "In tandem, CD4+ T cells further potentiate the sensitivity of cancer cells to ferroptosis by secreting TNF-α, which binds to TNF-α receptor 1 (TNFR1) on the cancer cells." (PMID 38217037, 2024). "Conversely, the findings of other studies have revealed reductions in the proportions of NK cells and CD8+ T cells in patients with cancer, whereas there is an increase in the CD4+/CD8+ T-cell ratio." (PMID 38404585, 2024). "Some evidence indicates that T lymphocytes, besides providing an immune response to present cancer cells, are able to induce EMT in cancer cell lines via produced cytokines, and it concerns both CD4+ and CD8+ T cells." (PMID 39201656, 2024). "Vaccination against cancer induces an anticancer CD4+/CD8+ T-cell response specific to cancer antigens." (PMID 39092051, 2024). "A single-cell pan-cancer study last year detected a novel CD4+/CD8+ T-cell subtype characterized by a high expression of heat shock protein genes such as HSPA1A, HSPA1B, and other stress-response-related genes, known as the stress response (TSTR)." (PMID 38629070, 2024). "A slight enrichment of CD4+ and CD8+ T cells in NECs and of cancer-associated fibroblasts and macrophages (M2-like) in NET G3." (PMID 38729995, 2024). "For example, in almost every cancer the TUBB mRNA expression level was positively related to the abundance of CD4+ Th1 cells." (PMID 38756529, 2024). "In conclusion, anti-CD4 CAR CD8-LVs were able to convert CD8 T cells into powerful cytotoxic T cells that lysed the CD4 cancer T cells in murine AITL biopsies." (PMID 39272178, 2024). "We also demonstrated that in PDAC an active APM mirrored by the close proximity of CD4+ helper T cells to APCs correlated positively with the proximity of CTL to cancer cells." (PMID 38474199, 2024).
cancer (continued). "DLAT was related to RNA modification genes, DNA methylation, immune infiltration, and immune infiltration cells, including CD4+ T cells, CD8+ T cells, Tregs, and cancer-associated fibroblasts." (PMID 39574473, 2024). "Meanwhile, the FADS2 expression level was mainly upregulated in malignant tumor cells, epithelial cells, mast cells, and macrophages, whereas it was extremely low in CD4 Tconv cells, Treg cells, plasma cells, and neutrophils." (PMID 38905386, 2024). "Our results showing decreased CD4 CTLs in Ing4-deleted tumors correlating with metastasis and poor patient survival are consistent with the roles of CD4 CTLs in anti-cancer immunity." (PMID 38968186, 2024). "Analysis of full ROIs showed several cell-type signal trends, including a high macrophage signal in a subset of cancer tissue samples, and the highest CD4+ T-cell signal in a subset of normal/inflamed tissues." (PMID 38505585, 2024). "Though apCAF populations have been shown to impact antigen-specific CD4+ T cell responses in several models of cancer, the overall impact of apCAF-induced Treg cells on cancer outcomes remains largely understudied." (PMID 38668758, 2024). "They boost the host immunity during NSCLC immunotherapy by increasing Th1 lymphocytes and in IL‐12‐dependent manner, boosting the amount of IFN‐γ, and attracting CCR9 + CXCR3 + CD4 + T cells towards cancer cells." (PMID 38571678, 2024). "Most notably, CCNB1 expression demonstrated the strongest positive correlation with CD4+ Th2 T cell, CD4+ Th1 T cell, and common lymphoid progenitor cells across various cancer types." (PMID 38581717, 2024). "It is well known that T cell CD4+ epitopes are important targets of immunity against infectious diseases and cancer." (PMID 38217545, 2024). "The presence of CD47 in the majority of cancer types was observed to have a positive correlation with the infiltration of CD4 + T cell memory resting and CD4 + T cell Th2, in contrast to CD4 + T cell (non-regulatory) and CD4 + T cell Th1." (PMID 38720108, 2024). "Restoring Vhl reversed the presence of TIM3 and PD-1 in both CD8+ and CD4+ T cells, showing that the Vhl status of cancer cells affected T cell function." (PMID 38618956, 2024). "CD4+ T cells, mainly including CD4+ T-helper (Th) cells and Tregs, are also critical in cancer immunity." (PMID 39519285, 2024). "DC vaccines induces specific CD8+/CD4+ T cell responses, and the DC‐cell‐based cancer immunotherapy possesses promising future perspectives." (PMID 38783893, 2024). "It has been demonstrated that CD4+ T cells not only can play a key role in the activation and memory of cytotoxic CD8+ T cells but also that intratumor CD4+ T cells have a cytotoxic program that can directly kill cancer cells." (PMID 39268079, 2024). "It is relevant to note here that activated CD4+ T lymphocytes and cancer cells share the quality of being highly proliferative cells." (PMID 39062560, 2024). "Subsequent irradiation with a 808 nm laser promotes the maturation of dendritic cells, thereby increasing the activity of CD8+ and CD4+ T cells in cancer immunotherapy." (PMID 38566199, 2024). "S100A7 was associated with B cells, CD4+ T cells, CD8+ T cells, cancer-associated fibroblasts, macrophages, neutrophils, and mast cells." (PMID 38499391, 2024). "In this research, we discovered that ALG3 is capable of efficiently activating all 6 distinct kinds of immune cells (neutrophils, CD8+ T cells, macrophages, CD4+ T cells, dendritic cells, and B cells) in approximately 20 different types of cancer." (PMID 38329424, 2024). "Participants with cancer had significantly smaller populations of TEMRA among the CD4+ and CD8+ T cells than healthy controls." (PMID 38719807, 2024). "We also assessed the nearest neighbours of 8_IFNGMac macrophages, finding that the closest neighbours to 8_IFNGMac TAMs were other TAMs, followed by CD4 memory T cells, cancer cells and CD8 memory T cells." (PMID 38969631, 2024).